ENSG00000285446 (novel protein)
Gene: Protein-coding gene on chromosome 6 (116,399,395 to 116,463,696, forward strand). Ensembl gene ENSG00000285446.
Genetic constraint (gnomAD): Loss-of-function variants: 12 observed, 29 expected, observed/expected ratio (o/e) 0.41, 90% interval 0.26 to 0.67. Missense variants: 221 observed, 367.27 expected, observed/expected ratio (o/e) 0.6, 90% interval 0.54 to 0.67. Synonymous variants: 120 observed, 135.18 expected, observed/expected ratio (o/e) 0.89, 90% interval 0.76 to 1.03.